MMP9 (matrix metallopeptidase 9)
Diseases named in the same sentence as MMP9 in open-access papers (continued):
Sharing a sentence is not in itself a finding about the gene and the disease.
heart failure (continued). "We have shown previously that during compensatory cardiac hypertrophy, MMP-2 expression was increased promoting angiogenesis while MMP-9 expression supersedes in de-compensatory heart failure promoting anti-angiogenesis." (PMID 24711742, 2014). "We have previously reported the role of anti-angiogenic factors in inducing the transition from compensatory cardiac hypertrophy to heart failure and the significance of MMP-9 and TIMP-3 in promoting this process during pressure overload hemodynamic stress." (PMID 22479323, 2012). "Transcript levels of several established biomarkers, including Spp1, Sfrp1, Sfrp2, Tnc, Vim, Mmp9, and Tnfrsf1a, and several inflammatory markers that are known to be activated in heart failure, such as Cd44, Cd83, Ccl7, Irf7, and Nr4a2, were upregulated in the Myh6-McmTamDspfl/fl cardiomyocytes." (PMID 40608429, 2025). "However, ACEI has also been found to reduce both MMP-2 and MMP-9 levels in another experimental model of heart failure." (PMID 37122872, 2023). "In previous studies, the expression of MMP-2 and MMP-9 increased in the left ventricular myocardium in patients with dilated cardiomyopathy, and the activation of MMP-2 and MMP-9 occurred in the myocardium of mice with heart failure, accompanied by extensive collagen deposition degeneration." (PMID 36771445, 2023). "Additionally, an increase in MMP-2 and MMP-9 produces extracellular matrix degradation, reduces the density of transverse tubules, and alters the management of Ca2+ in the myocardium of heart failure patients." (PMID 36831306, 2023). "This medication is approved for heart failure and edema, and may lower MMP-9 according to animal studies." (PMID 37430349, 2023). "Most currently used drugs for heart failure can reduce MMP9 levels." (PMID 36140171, 2022). "Therefore, reduction of MMP9 activity is shown to be an interesting current target strategy in order to prevent the exacerbation of heart failure." (PMID 36140171, 2022). "During diabetic cardiomyopathies, gelatinase-B also called MMP-9 activated via Ras/Raf/MEK/ERK signaling cascade causes extensive degradation of ECM and decreases matrix turnover, which is associated with several cardiac abnormalities and heart failure." (PMID 33747350, 2021). "Accordingly, MMP‐9 was shown to be up-regulated during heart failure." (PMID 31932967, 2021). "Induction of heart failure in rats has significantly increased circulating NT-proBNP (980 ± 116.71 pg/ml), MMP9 (15.85 ± 0.57 ng/ml), troponin-I (3.09 ± 0.147 ng/ml), CK-MB (31.55 ± 1.69 ng/ml), renin (736 ± 45.8 pg/ml), urea (52.1 ± 1.57 mg/dl), and creatinine (0.92 ± 0.04 mg/dl)." (PMID 31053170, 2019). "Also patients with Chagas heart disease complicated by heart failure had higher serum levels of MMP-9." (PMID 30572657, 2018). "The influence on the expression of MMP9 in atrial tissue by acquired factors, such as mitral valve disease, heart failure, ischemia and medication may outweigh the effect of a single genetic variant." (PMID 27070579, 2016). "In this study, we speculate that there is epigenetic silencing of TIMP4 in heart failure which allows the MMP9 to increase." (PMID 27396717, 2016). "In particular, an increase of TIMP-1 appears associated with the raising of circulating levels of MMP-2 and MMP-9, not only in patients at the final stage of heart failure (or in the acute state of decompensation), but also in patients with subclinical heart failure." (PMID 26495844, 2015). "Additionally, circulating MMP-2 and MMP-9 levels can reflect the effectiveness of treatment in heart failure patients and help identify those who may benefit from therapies targeting the MMP pathway." (PMID 39200884, 2024). "Moreover, to compare the physiological relevance of MMP-2 and MMP-9 in heart failure between the animal model and humans, we analyzed the expression of MMP-2 and MMP-9 in the left ventricle tissue of donated patient samples using publicly available GEO datasets." (PMID 36834504, 2023).
heart failure (continued). "MMP-2 and MMP-9 circulating levels can serve as indicators of efficiency of the therapy provided to heart failure (HF) patients, as well as for identification of patients who could benefit from particular therapeutic intervention via modification of MMP pathway." (PMID 32486345, 2020). "Further Spearman correlation analysis suggested that the MMP-2 but not MMP-9 could be used as an independent risk factors for heart failure diagnosis, which was consistent with the results of George J’s study。." (PMID 32354356, 2020). "Given that MMP-9 is an AP-1 target gene involved in cardiac remodeling, myocardial dysfunction and progression of heart failure, these findings suggest that miR-146a might be a new and promising therapeutic tool for treating cardiac disorders associated with enhanced inflammation in the heart." (PMID 26112171, 2015). "In a rat model of heart failure, pravastatin suppressed the increase in myocardial MMP-2 and MMP-9 activity." (PMID 39200884, 2024). "Signs of heart failure and LVEF decrease to <40% was recorded in 4 patients with elevated mRNA and protein expression of PGLYRP1, CAMP, MMP9 and CEACAM8 at baseline and after the initial chemotherapy dose." (PMID 39273682, 2024). "The tissue inhibitor of matrix metalloproteinase 4 (TIMP4) is a modulator of matrix metalloprotease 9 (MMP9), which regulates the pathological cardiac remodelling process, and it has been demonstrated that TIMP4 is reduced in heart failure." (PMID 39596076, 2024). "The levels of ANP, BNP, NT-ProBNP, PICP, MMP-2, MMP-9, and TIMP-1 in rat serum reflect the severity of heart failure, and the level of cAMP in myocardial tissues can reflect the activity of the cAMP signaling pathway." (PMID 38402401, 2024). "H2S also provides a clinical possibility for the prevention and treatment of heart failure by upregulating MMP2, downregulating MMP‐9 and TIMP‐3, and promoting angiogenesis through the eNOS‐NO pathway." (PMID 36478328, 2023). "The activity of MMP-9 increases in patients with dilated cardiomyopathy, and the expression of MMP-9 is significantly higher in patients with heart failure for any reason." (PMID 35035498, 2022). "In both experimental and clinical forms of heart failure, there is an increase in the cardiac content of MMP-2 and MMP-9." (PMID 33806909, 2021). "RT-qPCR showed that expression levels of the heart failure markers (ANP and BNP) and the fibrotic markers (α-SMA, TIMP2, and MMP9) were significantly higher in the DAC group than in the sham group." (PMID 34150870, 2021). "It was shown that in a rat model of heart failure, pravastatin suppressed the increase in myocardial MMP-2 and MMP-9 activity." (PMID 32486345, 2020). "By univariate analysis, there were positive relations between cardiovascular death or hospitalization for heart failure during the 3-year follow-up and the baseline levels of MMP-2 (P = 0.03), MMP-8 (P = 0.002), and MMP-9 (P = 0.03)." (PMID 23967183, 2013). "Treatment with H2S donors could inhibit the transition from compensatory hypertrophy to heart failure by inducing the production of MMP‐2, inhibiting the expression of TIMP‐3 and MMP‐9, and promoting the synthesis of VEGF." (PMID 36478328, 2023). "These children without proper treatment could eventually develop heart failure, so we assume that urinary MMP-9 levels could indicate disease outcome." (PMID 39466144, 2025). "Metalloproteinase-9 (MMP-9) may be an independent marker for suspecting and predicting the development of heart failure in children with rheumatic heart disease, furthermore, the level of MMP-9 correlates well with the severity of heart failure." (PMID 35626917, 2022). "Other heart failure related biomarkers which have been explored in patients who underwent ECLS include dynamic BNP, galectin-3, ST2, matrix metalloproteinase-9 (MMP-9), tissue inhibitors of metalloproteinase-1 (TIMP-1), MMP-2, osteopontin, MR-proANP, proADM, and copeptin." (PMID 33513858, 2021).
heart failure (continued). "We agree that some biomarkers, including MMP-2 and MMP-9, may reflect myocardial injury or heart failure regardless of T. cruzi infection." (PMID 31578449, 2019). "DNA methyltransferases such as DNMT3 and DNMT1 may mediate the cardiac remodelling in the development of heart failure through de novo methylation of DNA of non-coding regions, with impacts on the genetic expression of proteins with significant roles, such as MYH7, MYH6 and MMP9." (PMID 39596076, 2024). "Yet, most studies were done in selected populations (e.g., patients with heart failure, atrial fibrillation or primary aldosteronism), reported on a single MMP (i.e., MMP-2, MMP-9 and TIMP-1) and did not adjust for potential confounders." (PMID 32668720, 2020). "Among Tc+ individuals without cardiac insufficiency, only the MMP-2/MMP-9 ratio differed between those with and without ECG changes." (PMID 25275382, 2014).
liver cancer (89 papers, 2010 to 2025). An epithelial or non-epithelial malignant neoplasm that arises from the liver. "Hyperactivation of PI3K/PTEN/Akt/mTOR axis is implicated in liver cancer cell proliferation and migration by activating matrix metallopeptidase 9 (MMP9)." (PMID 38965615, 2024). "In terms of the diagnostic value in liver cancer, the expression of MMP9, MIR4435-2HG, and DUXAP8 has the potential to differentiate between normal individuals and HCC patients." (PMID 35201491, 2021). "Matrix metalloproteinases (MMPs) are major hydrolytic enzymes degrading almost all ECM components and the basement membrane, and previous studies have suggested that MMP2/MMP9 were closely associated with the invasion and metastasis of liver cancers." (PMID 31988091, 2020). "Abnormal expressions of MMP2/MMP9 were often observed in tumor tissues or cancer cell lines and were associated with tumor metastasis in many cancers including liver cancer." (PMID 31988091, 2020). "Previous study has reported associations between high expression of MMP2 or MMP9 and tumor aggressiveness in liver cancer." (PMID 30591064, 2018). "However, the role of PKR in the MMP-9 regulation in cardiomyocyte and hepatic cancer cells and the underlying molecular mechanism is unclear." (PMID 36432152, 2022). "The MIDN/CTNNB1/MMP9 axis promotes liver cancer progression via inducing a suppressive tumour immune microenvironment." (PMID 40111059, 2025). "Under the combined action of GM-CSF and oxidative stress, the protein expression of MMP-2 and MMP-9 in liver cancer cells was significantly increased, and the inhibitory effect of SHP-1 was insignificant." (PMID 38644382, 2024). "In liver cancer cells, MMP-9 has been found to interact with B-cell lymphoma 2 (BCL-2), an anti-apoptotic protein that prevents cell death." (PMID 38575697, 2024). "Matrine extracts can inhibit the expression of MMP9 and NF-κB to inhibit the invasion of liver cancer cells." (PMID 38582921, 2024). "Studies have found that knockdown of lncRNA-PVT1 can downregulate the expression of MMP9, and regulating the expression of MMP9 by knocking down lncRNA-PVT1 can increase the apoptosis rate of liver cancer cells by 16.2%." (PMID 36164442, 2022). "The purpose of this article is to explore the specific effect and mechanism of lncRNA-PVT1 on liver cancer rats by regulating the expression of MMP9." (PMID 36164442, 2022). "In the study of the specific effect and mechanism of lncRNA-PVT1 on liver cancer rats by regulating the expression of MMP9, this article summarizes and analyzes the research experience and results of a large number of predecessors." (PMID 36164442, 2022). "In order to explore the specific effect and mechanism of lncRNA-PVT1 on liver cancer rats by regulating the expression of MMP9, a large number of related materials were consulted." (PMID 36164442, 2022). "The overexpression of MMP-9 (Gelatinase B) highly participates in the progression of pathetic cardiac remodeling and liver cancer metastasis." (PMID 36432152, 2022). "Although research has shown that M2 macrophages can alter miR-149-5p to increase the expression of MMP-9 in liver cancer, in our study, MMP-9 and M2 macrophages were negatively correlated in LIHC." (PMID 35178444, 2022). "In our study, we also evaluated the influence of Fascin-1 on MMP2 and MMP9 expression in liver cancer cells." (PMID 34897283, 2021). "The inhibition of MMP‐9 expression in liver cancer can reduce the invasiveness and migration of cancer cells." (PMID 34026068, 2021). "First, according to the western blot experiment, the expression of Cyclin D1, MMP2, and MMP9 decreased significantly, indicating that the overexpression of miR-141 can inhibit the proliferation, migration, and invasion of liver cancer cells." (PMID 34675977, 2021). "Similar with their findings, we proved that Fascin-1 knockdown decreased MMP2 and MMP9 expression, and increased Sorafenib sensitivity in liver cancer cells." (PMID 34897283, 2021).
liver cancer (continued). "TC counts and MMP9 expression in liver cancer tissues were measured using immunohistochemistry, western blotting, and RT-PCR." (PMID 34376644, 2021). "In this systematic review, only one in vivo study (10%) reported a decrease in the levels of MMP-2 and MMP-9 in liver cancer after treatment with carvacrol, the majority 8.6% (n = 6) were in vitro studies." (PMID 34305611, 2021). "So, it is reasonable that LKB1 inhibits the metastasis of GSTA1 overexpressed liver cancer cells by downregulating the expression of MMP-9." (PMID 31892975, 2020). "Use of miR-338-3p can disrupt liver cancer cell invasion via blocking Smo-mediated MMP-9 expression in SMMC-7721 cells." (PMID 29734668, 2018). "Ardipusilloside I, a compound isolated from A. pusilla (Jiu-Jie-Long), inhibits liver cancer survival, invasion and metastasis by down-regulating MMP-9 and MMP-2 and activating Rac 1 to enhance E-cadherin activity." (PMID 26828466, 2016). "Additionally, in HepG2 liver cancer cells, vanillin reduced the gelatinolytic activity of matrix metalloproteinase-9 (MMP-9) by suppressing the nuclear factor kappa B (NF-κB) signaling cascade, highlighting its multifaceted role in curbing cancer spread." (PMID 41590042, 2025). "This study may contribute to the development of novel, potent, and selective MMP-9 inhibitors for liver cancer treatment in the future." (PMID 40871054, 2025). "Administration of HIF-1α inhibitors can block the upregulation of MMP2 and delay the progression of liver cancer, providing further verification of the conclusion that the HIF-1α/MMP2 or HIF-1α/MMP9 signaling pathways are involved in the occurrence and development of liver cancer." (PMID 40563539, 2025). "Previous research has suggested that the Wnt signaling might promote the expression of MMP-2 and MMP-9 in liver cancer." (PMID 38468952, 2024). "This disruption of the MMP-9-BCL-2 interaction leads to decreased cell survival and increased susceptibility to apoptosis, further contributing to the anti-cancer effect of AgNPs in liver cancer cells." (PMID 38575697, 2024). "SHP-1 inhibited the protein expression of MMP-2 and MMP-9 in liver cancer cells." (PMID 38644382, 2024). "However, with the gradual progression of liver cancer, Nrf2 will promote the expression of MMP9 and is a key factor in promoting the proliferation, metastasis, invasion, and other malignant biological behaviors of HCC." (PMID 37174639, 2023). "On the basis of these observations, we hypothesized that MTs in the coding region of NRF2 might cause aberrant transcriptional activity and have some effect on MMP9 transactivation when BRAF MT is also present in liver cancer cells." (PMID 34069882, 2021). "We analyzed the correlation between MMP9 and immune checkpoints in liver cancer." (PMID 33643387, 2021). "We detected the protein and mRNA level of OGFR, MOR, uPA and MMP-9 in Hep3B/HepG2 cells to explore the molecular mechanisms through which morphine could affect the liver cancer cells." (PMID 33968773, 2021). "It has been reported that HD (50 μM) suppresses human hepatic cancer (HepG2) cell proliferation by inhibiting matrix metalloproteinase-9 (MMP-9) enzymatic activity, inhibiting phosphorylation of p38 and JNK signaling pathways and suppressing the NF-kB and activator protein 1 (AP-1) pathway." (PMID 32863858, 2020). "Resveratrol inhibits adhesion, migration, invasion and MMP-9 expression in liver cancer cells." (PMID 26828466, 2016). ", down-regulates MMP-9 and NF-κB and inhibits invasion in liver cancer cells." (PMID 26828466, 2016). "Another study also revealed that MMP9 could be upregulated by ASIC1α in liver cancer." (PMID 41312374, 2025).